PPARA (peroxisome proliferator activated receptor alpha)
Diseases named in the same sentence as PPARA in open-access papers (continued):
Sharing a sentence is not in itself a finding about the gene and the disease.
cardiac hypertrophy (continued). "Therefore, the elevated level of PPARα in DOCA-salt rats receiving URB597 may be responsible for reduced cardiac hypertrophy, as observed in our previous study." (PMID 30223427, 2018). "Therefore, although our study may provide additional evidence showing the application of PPARα for the treatment of cardiac hypertrophy, further investigation is required to clarify this point." (PMID 27807394, 2016). "Therefore, we hypothesized that PPARα, NF-κB, adiponectin, and cardiac hypertrophy may be interrelated." (PMID 27807394, 2016). "Moreover, AMPK activator can upregulate PPARα signaling pathway to inhibit cardiac hypertrophy." (PMID 27413362, 2016). "Therefore, we hypothesized that such a link may also exist between PPARα, NF-κB, adiponectin, and cardiac hypertrophy." (PMID 27807394, 2016). "Therefore, PPARα may be the mediator, at least in part, of the energy metabolic substrate switch from fatty acid oxidation to glycolysis during pathological cardiac hypertrophy." (PMID 25753319, 2015). "In addition, while this study primarily focuses on the role of the USP4/PPARα signaling pathway in Lgr6‐mediated regulation of pathological cardiac hypertrophy, we acknowledge that other potential mechanisms may exist and warrant further investigation in the future." (PMID 40211903, 2025). "We then transfected AAV9‐cTnT‐PPARα and AAV9‐cTnT‐shLgr6 into the hearts of mice to further investigate the role of PPARα in Lgr6‐regulated cardiac hypertrophy." (PMID 40211903, 2025). "CGAs can regulate NF-κB and PPARα pathways, lower HIF-1α expression, and suppress cardiac apoptotic signaling, thus executing beneficial effects against cardiac hypertrophy and heart failure (HF)." (PMID 38612964, 2024). "CGA-enriched chrysanthemum extract (CME) prevents myocardial hypertrophy by targeting HIF-1α and PPARα pathways in rats with renal hypertension and H9C2 cells with stimulation of ANG II-hypoxia." (PMID 38612964, 2024). "A metabolic shift from fatty acid (FAO) to glucose oxidation (GO) occurs during cardiac hypertrophy (LVH) and heart failure with reduced ejection fraction (HFrEF), which is mediated by PGC-1α and PPARα." (PMID 38259303, 2023). "A number of mechanisms, such as downregulation of PPARα and PGC1α-mediated transcription, have been identified for the reduced FAO in cardiac hypertrophy, but the driver for the upregulation of glycolysis remains elusive." (PMID 35575090, 2022). "Fibrate has been reported to inhibit cardiac hypertrophy and heart failure through suppression of PI3K/Akt/mTOR signaling and regulation of HMGB1 expression, in addition to activation of PPARα." (PMID 35055179, 2022). "Our findings indicate that Fabp3-defect exacerbates cardiac hypertrophy and heart dysfunction, resulting in defective FAO, and increased glycolysis by impairing the PPARα signaling pathway." (PMID 34458345, 2021). "We further determine the effect of PPARα activation on the expression of SCAD and pathological cardiac hypertrophy in vivo and in vitro." (PMID 25753319, 2015). "A mouse model of cardiac hypertrophy induced by TAC was used to investigate the expression of both HMGB1 and PPARα in the hearts of the model mice." (PMID 24523730, 2014). "Further evidence for a putative role of PPARα in cardiac hypertrophy comes from studies on fibroblast growth factor 21 (FGF21), which is expressed in and released by cardiomyocytes through a PPARα - dependent mechanism." (PMID 24938300, 2014). "In cardiovascular disease, USP28 has recently been found to be involved in the regulation of diabetic cardiomyopathy by targeting peroxisome proliferator-activated receptor α (PPARα) 15, while the function of USP28 in cardiac hypertrophy is still unknown." (PMID 39431010, 2024). "Furthermore, the cells transfected with Ythdf2 plasmid had increased mRNA and protein expression of cardiac hypertrophy markers ANP, BNP, and β-MHC, whereas PPARα and CPT-1a were significantly decreased relative to control groups." (PMID 35383152, 2022).
cardiac hypertrophy (continued). "Similarly, knockdown of MIAT decreased cardiac hypertrophy markers ANP, BNP, and β-MHC, whereas PPARα and CPT-1a mRNA and protein levels were increased." (PMID 35383152, 2022). "In contrast to studies showing that a global reduction of PPARα can have a deleterious impact, we did not observe any dysfunction or cardiac hypertrophy in cPPAR-/- mice at baseline." (PMID 35259201, 2022). "In western blot analysis and RT-qPCR assays, the cells transfected with MIAT plasmid had increased mRNA and protein expression of cardiac hypertrophy markers ANP, BNP, and β-MHC, whereas PPARα and CPT-1a were notably decreased relative to mock or scramble groups." (PMID 35383152, 2022). "Similarly, knockdown of Ythdf2 decreased cardiac hypertrophy markers ANP, BNP, and β-MHC, whereas PPARα and CPT-1a mRNA and protein levels were increased." (PMID 35383152, 2022). "This indicates that at least under physiological conditions, a decline in PPARα decreases cardiac Plin2 without inducing protein oxidation or cardiac hypertrophy." (PMID 35259201, 2022). "Therefore, we performed the present study to confirm the effect of DAPA towards cardiac hypertrophy in AAC-induced mice and to explore the regulatory effect on Plin5/PPARα signal axis." (PMID 34630108, 2021). "We suggested that DAPA mediated the Plin5/PPARα signal axis, and ultimately affected the expression level of PDK4 and HMGCS2, myocardial cell metabolism, and relieve the pathological progression of cardiac hypertrophy." (PMID 34630108, 2021). "We demonstrated that DAPA could activate the Plin5/PPARα signaling pathway and further significantly promoted the expressions PDK4 and HMGCS2 in cardiac hypertrophy." (PMID 34630108, 2021). "Here, our in vivo and in vitro results reveal the potential mechanism of the FABP3-mediated PPARα pathway in cardiac hypertrophy and in FAO/glycolysis balance by directly binding to PPARα, promoting its stability, and underpinning its transactivation in Mlycd and Gck." (PMID 34458345, 2021). "Furthermore, the agonist of PPARα, fenofibrate, attenuated TAC-induced cardiac hypertrophy in both wild-type (WT) and Fabp3-null mice." (PMID 34458345, 2021). "We next sought to determine whether activating PPARα may rescue the pro-hypertrophic effects of Fabp3 defect after TAC operation and search for clinical benefits on the treatment of cardiac hypertrophy." (PMID 34458345, 2021). "Hrvey reported that Nox2 was a key signaling molecule in the pathological reaction of PPARα down-regulation leading to cardiac hypertrophy, which proved that the molecular mechanism of PPARα in cardiac hypertrophy from the negative side." (PMID 34630108, 2021). "In addition, activation or knockout of PPARα, another member of the PPAR family, by application of an agonist or genetic manipulation improves cardiac hypertrophy induced by chronic pressure overload." (PMID 30620754, 2019). "Findings in PPARα-null mice and MHC-PPARα mice suggest that the lack of PPARα or increase in its level leads to cardiac hypertrophy and dilated cardiomyopathy (DCM)." (PMID 26981112, 2016). "Moreover, cardiac specific PPARα-transgenic mice display enhanced FAO, increased lipid droplets, and ventricular hypertrophy." (PMID 25815008, 2015). "In PPARα-/- mice, cardiac hypertrophy is induced, and also in mice lacking PGC-1α, cardiac dysfunction becomes evident." (PMID 24938300, 2014). "After demonstrating the effect of PPARα on HMGB1 expression and localization in cardiomyocytes, we next investigated whether this effect could influence the progression of cardiac hypertrophy." (PMID 24523730, 2014). "As regard the pleiotropic effects of PPARα on inhibiting glucose oxidation, while activating FAO, we aimed to determine whether FABP3 interacts with PPARα and modulates its transcriptional capacities on FAO/glycolysis genes, and further is involved in the advance of cardiac hypertrophy." (PMID 34458345, 2021).
cardiac hypertrophy (continued). "Moreover, a statin was reported to inhibit cardiac hypertrophy by inhibiting negative cross talk between nuclear factor-κB (NF-κB) and PPARα." (PMID 27807394, 2016). "Moreover, cardiac expression of PGC-1α and PPARα in exercise-trained mice showed a relative increase, findings in agreement with the idea that cardiac hypertrophy in this context is not pathological." (PMID 27677409, 2016). "More importantly, treatment with irbesartan remarkably attenuated ACE2-dificiency induced myocardial hypertrophy and ultrastructure injury along with augmentation of cardiac PPARγ level, without having a differential effect on the expression of PPARα and PPARδ." (PMID 24067190, 2013).
hypertriglyceridemia (118 papers, 2005 to 2026). A laboratory test result indicating elevated triglyceride concentration in the blood. "Apoa5 has been identified as a direct downstream target of PPARα and encodes for an apolipoprotein that aids in regulating triglyceride homeostasis, with the downregulation of this protein resulting in hypertriglyceridemia in mammals." (PMID 39453152, 2024). "Indeed, PPARα agonists, such as fibrates, have been used to treat hypertriglyceridemia and reduce cardiovascular risk." (PMID 21603234, 2011). "In addition, since serum bilirubin levels have been negatively associated with hypertriglyceridemia, we analyzed the levels of triglycerides in plasma and liver, as well as the expression of PPARα, and key genes regulated by PPARα involved in glucose and lipid oxidation metabolisms in the liver." (PMID 34943131, 2021). "Pemafibrate, a selective peroxisome proliferator‐activated receptor α (PPARα) modulator, is mainly prescribed for hypertriglyceridemia." (PMID 40932833, 2025). "PPARα is highly expressed in the liver and is the molecular target of a series of fibrates used for treatment of hypertriglyceridemia." (PMID 38375358, 2024). "Short-term use of pemafibrate (PEM), a selective modulator of peroxisome proliferator-activated receptor alpha, has been reported to improve abnormal liver function in patients with nonalcoholic fatty liver disease with hypertriglyceridemia (HTG-NAFLD)." (PMID 38828415, 2024). "Another area of interest lies in elucidating the pleiotropic properties of agents that ameliorate hypertriglyceridemia, particularly peroxisome proliferator-activated receptor alpha (PPARa) agonists such as fibrates." (PMID 39057711, 2024). "Further study found that the interaction between hypertriglyceridemia and acute promyelocytic leukemia is mediated by the cooperation of peroxisome proliferator-activated receptor-alpha with PML/RAR alpha fusion protein on the super enhancer." (PMID 37441519, 2023). "The FDA-approved fibrate drugs act selectively on PPARα to lower blood lipids and treat hypertriglyceridemia." (PMID 37417957, 2023). "Fenofibrate is a hypolipidemic peroxisome proliferator-activated receptor α (PPARα) agonist used clinically to reduce hypercholesterolemia and hypertriglyceridemia." (PMID 37935669, 2023). "In looking more specifically at ligands for PPARα, a synthetic ligand such as fenofibrate (fibrates) is widely used in the treatment of hypertriglyceridemia in order to reduce serum triglyceride levels." (PMID 35204062, 2022). "Pemafibrate is widely used to treat hypertriglyceridemia owing to its high clinical efficacy and minor disadvantages compared with those of conventional PPARα agonists." (PMID 35845076, 2022). "In our model, CCE at the lowest dose increased the relative mRNA expression of Pparα in the liver and tended to decrease hypertriglyceridemia induced by an HFD." (PMID 35448490, 2022). "A similar effect was shown by Rosa rugosa extract, rich in flavonoids, which reduces hypertriglyceridemia by acting as PPARα agonist." (PMID 36501129, 2022). "Fibrates are agonists of peroxisome proliferator-activated receptor alpha (PPARα) that are widely used as therapeutic agents to treat patients with hypertriglyceridemia." (PMID 35053222, 2022). "The PPARα agonist fenofibrate, which is approved for the treatment of hypercholesterolemia and hypertriglyceridemia, was shown to attenuate behavioral disruption and dopaminergic dysfunction in MIA offspring." (PMID 34681249, 2021). "Fenofibrate has been used clinically for decades to manage hypertriglyceridemia, and its action is mediated by the peroxisome proliferator-activated receptor alpha (PPARα), a nuclear receptor that regulates the genes for fatty acid catabolism." (PMID 33107777, 2020). "Previously, pemafibrate, a novel selective peroxisome proliferator-activated receptor alpha modulator, was suggested as a promising drug in hypertriglyceridemia." (PMID 32872333, 2020).
hypertriglyceridemia (continued). "Guidelines recommend fibrates (PPARα agonists) and omega-3 fatty acids for the management of hypertriglyceridemia, usually as an add-on to primary statin treatment." (PMID 31164165, 2019). "After statins, guidelines recommend peroxisome proliferator-activated receptor alpha (PPARα) agonists—fibrates—for management of hypertriglyceridemia." (PMID 31164165, 2019). "In the liver, PPARα promotes fatty acid oxidation, which makes it a possible drug target for treating hypertriglyceridemia." (PMID 29706895, 2018). "PPARα agonists such as fenofibrate have been used clinically for several decades and provide a well-established cardiovascular benefit to patients with hypertriglyceridemia." (PMID 28874443, 2017). "Peroxisome proliferator-activated receptor alpha (PPARα) ligands include fibrates that are commonly used for the treatment of hypertriglyceridemia and WY14,643 and GW7647." (PMID 25007880, 2015). "Hepatic suppression of Pparα was also identified as a mechanism contributing to serum hypertriglyceridemia induced by a high-fructose diet." (PMID 26458107, 2015). "PPARα can be activated by natural lipophilic ligands such as fatty acids and by drugs approved for the treatment of hypertriglyceridemia, such as fibrates." (PMID 23431284, 2013). "Fibrate drugs function as agonists of PPARα and have been used for the treatment of hypertriglyceridemia." (PMID 21861924, 2011). "Our previous study also showed that plasma level of BH4 was significantly increased by PPARα agonist fenofibrate in patients with hypertriglyceridemia." (PMID 22190909, 2011). "Fibrates (peroxisome proliferator activated receptor alpha (PPARα) agonists) are a class of drug that is used to primarily treat hypertriglyceridemia and low HDLC." (PMID 18547436, 2008). "Activators of PPARα, such as fibrates, lower circulating levels of lipid and are commonly used to treat hypertriglyceridemia." (PMID 16091142, 2005). "Our studies indicate hypertriglyceridemia induced by fructose feeding greatly reduces the hepatic expression of both PPARα protein and mRNA levels." (PMID 16091142, 2005). "One of the mechanisms that contribute to serum hypertriglyceridemia in this model is suppression of hepatic PPARα." (PMID 16091142, 2005). "The current studies indicate that hypertriglyceridemia induced by high fructose feeding leads to major reduction in the steady-state levels of both PPARα protein and mRNA." (PMID 16091142, 2005). "Pemafibrate, an SPPARMα, suppresses only process, but, our present date showed potent anti hypertriglyceridemia effect of pemafibrate in the alcohol induced TG increase suggests that PPARα activity is largely involved in the mechanism of alcohol induced TG increase." (PMID 39802168, 2025). "Similarly, drugs like gemfibrozil, and fenofibrate, the PPARα agonists prescribed for the treatment of hypertriglyceridemia, are able to promote Th2 responses and hold promise in treatment of autoimmune diseases." (PMID 40943243, 2025). "As fatty acid is the main material for TG synthesis, HPPs might alleviate hypertriglyceridemia by activating hepatic PPARα gene expression to reduce fatty acid levels." (PMID 36839401, 2023). "In eWAT, upregulation of Pparα has been demonstrated to decrease hypertriglyceridemia." (PMID 35308230, 2022). "The upregulation of Cpt1 in Wdr13−/0 liver may be a result of upregulated Pparα and liver hypertriglyceridemia." (PMID 33292732, 2020). "PPARα agonists, fibrates, are used to treat hypertriglyceridemia." (PMID 32948821, 2020). "PPARα improves systemic lipid metabolism; thus, PPARα agonists can improve hypertriglyceridemia." (PMID 29738435, 2018). "The data in this study suggest that the synergistic effects of Fsp27 silencing and PPARα activation could be exploited therapeutically to reduce diet-induced body weight gain, visceral obesity, hypertriglyceridemia, and steatohepatitis." (PMID 28874443, 2017).
hypertriglyceridemia (continued). "Taken together, mouse models suggest that PPARα functions to increase fatty acid use in the fasting state, and that in the context of a high-fat diet PPARα, inducing fatty acid catabolism, might prevent hepatocellular fat accumulation and hypertriglyceridemia." (PMID 23431284, 2013). "Additionally, PPARα downregulation leads to hypertriglyceridemia." (PMID 40947814, 2025). "PPAR agonists can induce browning of WAT, and administration of a PPARα agonist (fenofibrate) showed effective control of hypertriglyceridemia and reduction of adipose tissue in a patient with MSL." (PMID 38271099, 2024). "Saroglitazar acts as a dual PPARα/γ agonist, first approved in India for the treatment of patients with T2DM and hypertriglyceridemia." (PMID 38891828, 2024). "Furthermore, according to our molecular docking results, the nanoparticle components, such as Helix-Y12 and Tzeax, might activate both PPARα and PPARβ/δ, which would help us explain the protective effects against hypertriglyceridemia, vascular, and liver lesions." (PMID 37096195, 2023). "The hypertriglyceridemia in CREB3L3−/− mice was improved by the simultaneous ablation of PPARα, suggesting functional antagonism between PPARα and CREB3L3 in plasma triglyceride regulation." (PMID 30866796, 2019). "Fenofibrate, a peroxisome proliferator-activated receptor alpha (PPAR-α) agonist, has been used for decades to treat hypertriglyceridaemia and mixed dyslipidaemia." (PMID 24529079, 2014). "Synthetic PPARα agonists promote FAO by directing the activity of pathways for balanced lipid metabolism in the liver, which consequently supported a series of FDA-approved fibrate drugs for the treatment of hypertriglyceridemia." (PMID 37417957, 2023). "However, PPARα modulators that are used as triglyceride-lowering agents induce hepatic expression of ENPEP and ENPEP peptidase protects against hypertriglyceridemia." (PMID 37628732, 2023). "If statins are not successful, guidelines recommend peroxisome proliferator-activated receptor alpha (PPARα) agonists (fibrates) for the management of hypertriglyceridemia." (PMID 31461874, 2019). "PPARα There have been no studies proving the efficacy of PPARα agonists, such as bezafibrate or fenofibrate, which are extensively used in the treatment of hypertriglyceridemia but have no impact in NASH/NAFLD." (PMID 29247356, 2018). "However, it has also been reported that ACC inhibition might result in hypertriglyceridemia through decreasing polyunsaturated fatty acids which further led to SREBP1 induction and decreased PPARα and CPT1 activity." (PMID 36192786, 2022). "Fibrates are ligands of PPARα and commonly used to treat hypertriglyceridemia, and we have previously shown in lymphocytes that fibrates potently augment TRB3 expression, independent of PPARα expression." (PMID 24490110, 2013). "The aim of this work was to examine the effect of the PPARα agonist, ciprofibrate, on the CETP gene expression, in the presence and absence of apolipoprotein (apo) CIII induced hypertriglyceridemia, and its impact on the HDL metabolism." (PMID 19930639, 2009).